YTHDC2 (YTH N6-methyladenosine RNA binding protein C2)
Diseases named in the same sentence as YTHDC2 in open-access papers (continued):
Sharing a sentence is not in itself a finding about the gene and the disease.
lung carcinoma (12 papers, 2021 to 2025). "The present results indicated that smoking-related downregulation of YTHDC2 was associated with enhanced proliferation and migration in lung cancer cells, and appeared to be regulated by DNA copy number variation." (PMID 34326699, 2021). "In conclusion, the present results indicated that the downregulation of smoking-related YTHDC2 was associated with enhanced proliferation and migration of lung cancer cells, and appeared to be regulated by DNA copy number variation." (PMID 34326699, 2021). "The cylindromatosis (CYLD)/NF-κB pathway has been confirmed to be downstream of YTHDC2, and this axis is mediated by m6A modification in lung cancer." (PMID 40986143, 2025). "In lung cancer, the YTHDC2/eIF4GI complex triggers cap-independent translation initiation, and targeted specific demethylation of VEGFA m6A significantly reduced VEGFA expression." (PMID 40316995, 2025). "In lung cancer, YTHDC2 enhances the translation efficiency of lncZNRD1-AS1, further suppressing angiogenesis and tumorigenesis through the miR-942/Tensin 1 axis." (PMID 39098905, 2024). "Beyond mRNA regulation, YTHDC2 have also been shown to inhibit the malignant progression of lung cancer by regulating the levels of long non-coding RNAs (lncRNAs)." (PMID 38790013, 2024). "In vivo, confirmation of YTHDC2 overexpression inhibits lung cancer cell migration and proliferation." (PMID 39253534, 2024). "In the early stage, the team has demonstrated that YTHDC2 was downregulated in lung cancer cells and contributed to cell proliferation, migration and the EMT process." (PMID 39691597, 2024). "These contrasting roles of YTHDC2 in lung cancer underscore its context-dependent functions via different downstream targets, suggesting personalized therapeutic strategies based on individual patient profiles." (PMID 38790013, 2024). "This study provided evidence that m6A modification mediates YTHDC2-mediated downregulation of ZNRD1-AS1 in lung cancer and cigarette smoke-exposed cells." (PMID 36581942, 2022). "In our previous study it was demonstrated that YTH domain-containing 2 (YTHDC2), an m6A ‘reader’, was reduced in lung cancer and contributed to cell proliferation, migration and the epithelial-mesenchymal transition (EMT) process." (PMID 36581942, 2022). "Our previous study revealed that YTHDC2 is a cigarette smoking-drived gene in lung cancer, and it functions as a tumor suppressor through the CYLD/NF-κB signaling pathway, which is mediated by m6A modification." (PMID 36581942, 2022). "The in vivo and in vitro studies revealed that YTHDC2 overexpression inhibited the proliferation and migration of lung cancer cells as well as tumor growth in nude mice." (PMID 34326699, 2021). "When the pathological stage is considered, the expression of YTHDC2 mRNA in stage II lung cancer tissues in the TCGA LUAD and GSE41271 cohorts was significantly lower than that in stage I." (PMID 34326699, 2021). "The current results showed different YTHDC2 expression profiles and prognostic significance in patients with lung cancer." (PMID 34326699, 2021). "For invasion depth T stage, the mRNA expression of YTHDC2 in lung cancer tissues with T3 or/and T4 stages in the TCGA LUAD, TCGA LUSC and GSE30219 cohorts were also significantly lower than those in lung cancer tissues with T1 stage." (PMID 34326699, 2021). "CYLD/NF-κB is a vital downstream pathway that contributes to the tumor-suppressor role of YTHDC2 in lung cancer cells." (PMID 34326699, 2021). "The mRNA expression of YTHDC2 in lung cancer tissues was less than that in normal adjacent tissues in two GEO datasets, GSE32665 and GSE19188." (PMID 34326699, 2021). "Further in vitro and in vivo studies are needed to gain insights into additional m6A-dependent downstream mechanisms of YTHDC2 in lung cancer." (PMID 34326699, 2021).
lung carcinoma (continued). "Univariate Cox model and Kaplan-Meier survival analysis revealed that increased YTHDC2 mRNA expression was significantly associated with improved survival (HR<1, P<0.05) in GSE41271, GSE30219 and TCGA lung cancer datasets." (PMID 34326699, 2021). "Based on bioinformatics and tissue array IHC analyses, the mRNA and protein expression of YTHDC2 was downregulated in lung cancer tissues compared with that of normal tissues." (PMID 34326699, 2021). "The present study further explored the mechanisms of YTHDC2 dysregulation using the multi-omics data of lung cancer from TCGA database." (PMID 34326699, 2021). "Inhibition of SLC7A11 by sulforaphane or YTHDC2 (a m6A reader) induced the ferroptosis of lung cancer cells and suppressed the progression of lung cancer." (PMID 34722530, 2021). "The present study used the GEPIA online tool to analyze the expression of YTHDC2, and found it to be significantly decreased in several solid tumors, including the two most common subtypes of lung cancer, compared with its expression in normal tissues." (PMID 34326699, 2021). "The IHC results of lung cancer tissue arrays showed a significantly lower YTHDC2 expression in lung cancer tissues than that in normal tissues." (PMID 34326699, 2021). "Notably, reduced expression of YTHDC2 has been observed in lung cancer and cigarette smoke-exposed cells, correlating with smoking history, advanced stage, invasion depth, lymph node metastasis, and poor outcomes." (PMID 38790013, 2024). "In lung cancer, YTHDC2 decrease is modulated by copy number deletion." (PMID 39253534, 2024). "In addition, the bioinformatics and proteomics analyses demonstrated that YTHDC2 contributed to the initiation and progression of lung cancer." (PMID 34326699, 2021). "In addition, the expression of YTHDC2 in M1 lung cancer was significantly lower than that in M0 lung cancer in the TCGA LUSC cohort." (PMID 34326699, 2021). "The results revealed that YTHDC2 was reduced in lung cancer and cigarette smoke-exposed cells." (PMID 34326699, 2021). "YTHDC2 can promote 6PGD mRNA translation in lung cancer cells by means of m6A modification." (PMID 34497675, 2021). "Importantly, the xenograft animal model further validated the tumor-suppressor effect of YTHDC2 on lung cancer cell tumorigenesis in vivo." (PMID 34326699, 2021). "In addition, 5 Oncomine datasets were extracted to verify the YTHDC2 copy numbers in lung cancer, and a significantly decreased copy number was found." (PMID 34326699, 2021). "However, the role of YTHDC2 in other types of tumors, particularly lung cancer, remains unresolved." (PMID 34326699, 2021). "Furthermore, YTHDC2 decreased expression was modulated by copy number deletion in lung cancer." (PMID 34326699, 2021). "YTHDC2 targets miR-942 downstream from ZNRD1-AS1 through m6A-mediated regulation, reducing its stability and offering therapeutic potential for lung cancer proliferation and invasion." (PMID 40986143, 2025). "In lung cancer, METTL3 binds to the A859 site within the internal ribosome entry site of VEGFA 5’UTR, recruiting YTHDC2/eIF4GI complex to promote VEGFA translation and increase its expression." (PMID 39098905, 2024). "The copy number variation of YTHDC2 was further verified in CS-exposed BEAS-2B cells and several lung cancer cell lines using TaqMan qPCR." (PMID 34326699, 2021). "Consistent with YTHDC2, the CYLD mRNA expression in lung cancer tissues was lower than that in normal adjacent tissues in GSE32665 and GSE19188, as well as in GEPIA online tool." (PMID 34326699, 2021). "The results showed that the expression profiles of eight m6A regulators (ALKBH5, FTO, HNRNPC, METTL14, RBM15, YTHDC1, YTHDC2, and ZC3H13) were significantly different among the three different lung cancer subtypes (P < 0.01)." (PMID 34805165, 2021).
lung carcinoma (continued). "Contrary to observations in lung cancer 65, where YTHDC2 was reported to diminish SLC7A11 expression through reduced SLC7A11 mRNA stability, our findings reveal that YTHDC2 facilitates the upregulation of SLC7A11 expression by enhancing its translational efficiency in the epileptic condition." (PMID 39310099, 2024). "Based on the data of HPA, 50% of the lung cancer tissues showed no staining for anti-YTHDC2 antibody, while the 3 normal tissues showed low staining." (PMID 34326699, 2021). "YTHDC2 was shown to form complexes with eukaryotic translation initiation factor 4 gamma 1 (eIF4GI) and bind to the m6A methylation site of the vascular endothelial growth factor A (VEGFA) 5’UTR, thereby promoting its translation and accelerating lung cancer angiogenesis." (PMID 38790013, 2024).
breast carcinoma (10 papers, 2020 to 2025). "Basal-like subtypes and other breast cancer subtypes are associated with the m6A regulators YTHDC2, IGF2BP2, IGF2BP3 and RBM15, and luminal A and B subtypes are classified into two clusters according to the methylation status of these four regulators." (PMID 35721510, 2022). "Low expression of YTHDC2 was associated with worse recurrence-free survival in patients with HER2-positive breast cancer." (PMID 35562334, 2022). "We established YTHDC2-knocked-down cell lines using four breast cancer cell lines with different subtypes." (PMID 36245989, 2022). "In the present study, the YTHDC2 expression level showed a positive correlation with the stage of the breast cancers, suggesting that YTHDC2 is involved in the progression of breast cancer." (PMID 36245989, 2022). "For YTHDC2, its knockdown attenuates soft agar clonogenic and metastatic abilities of breast cancer cells." (PMID 36581942, 2022). "In the present study, we knocked down YTHDC2 expression in breast cancer cell lines including MCF-7, SK-BR-3, MDA-MB-231, and MDA-MB-468 and found that knockdown of YTHDC2 suppressed the sphere-forming and metastatic ability of them." (PMID 36245989, 2022). "To clarify the role of YTHDC2 in breast cancer, we knocked down the endogenous YTHDC2 expression by infecting MCF-7, SK-BR-3, MDA-MB-231, and MDA-MB-468 cells with lentivirus containing YTHDC2 shRNA." (PMID 36245989, 2022). "Although stemness and EMT markers, such as SOX2, c-MYC, and NANOG, were downregulated in several YTHDC2-knocked-down breast cancer cells, a common target gene of YTHDC2 in breast cancer cells was not identified." (PMID 36245989, 2022). "Knockdown of YTHDC2 attenuated the sphere-forming and the metastatic ability of breast cancer cells." (PMID 36245989, 2022). "We firstly investigated the correlation between breast cancer progression and YTHDC2 expression levels." (PMID 36245989, 2022). "For example, ZCRB1 was overexpressed in lymphoma, and ADH1C in cervical cancer and esophageal cancer, and YTHDC2 in breast cancer, gastric cancer, head and neck cancer, myeloma, and sarcoma." (PMID 34178026, 2021). "Therefore, our findings indicate that YTHDC2 is involved in the malignant progression of breast cancers." (PMID 36245989, 2022). "IGF2BP 2/3 and YTHDC2 were highly expressed in basal-like breast cancer." (PMID 35721510, 2022). "The sphere-forming and metastatic ability of breast cancer cells was significantly suppressed by the YTHDC2 knockdown, suggesting that the expression of genes related to stemness and metastasis was downregulated in the YTHDC2-knocked-down cells." (PMID 36245989, 2022). "In summary, our findings demonstrated that YTHDC2 contributes to breast cancer progression by regulating the expression of stemness transcription factors, indicating the potential of YTHDC2 as a therapeutic target for breast cancer patients." (PMID 36245989, 2022). "Here, we show that YTHDC2 is essential for breast cancer tumorigenesis and metastasis." (PMID 36245989, 2022). "We further investigated the metastatic ability of YTHDC2-knocked-down breast cancer cells in vivo." (PMID 36245989, 2022). "In this study, we investigated the roles of YTHDC2 in breast cancers." (PMID 36245989, 2022). "However, all of these genes that were altered by YTHDC2 knockdown are involved in cancer stemness and metastasis, suggesting that YTHDC2 plays important roles in malignant progression of breast cancer cells." (PMID 36245989, 2022). "Knockdown of YTHDC2 suppressed the sphere-forming and metastatic activity of breast cancer cells." (PMID 36245989, 2022). "The YTHDC2 expression levels tended to correlate with the progression of breast cancer, suggesting that the YTHDC2 molecule may be extensively involved in the exacerbation of breast cancer." (PMID 36245989, 2022).
breast carcinoma (continued). "Although the mRNA expression of stemness markers, such as SOX2, c-MYC, and NANOG, was reduced by YTHDC2 knockdown, the alteration of gene expression pattern was not the same for all of breast cancer cell lines." (PMID 36245989, 2022). "A negative correlation between FGFR4 expression and YTHDC2 levels was observed in the TCGA cohort of HER2-positive breast cancer patients." (PMID 35562334, 2022).
nasopharyngeal carcinoma (9 papers, 2020 to 2025). A carcinoma arising from the nasopharyngeal epithelium. "YTHDC2 activates the IGF1R/Akt/S6 signal axis to promote radiotherapy tolerance for nasopharyngeal carcinoma." (PMID 33748145, 2021). "YTHDC2 contributed to radioresistance in nasopharyngeal carcinoma (NPC) cells by binding to IGF1R mRNA and promoting the translation of the IGF1R transcript, leading to downstream activation of the IGF1R-AKT/S6 signaling axis." (PMID 33669361, 2021). "In summary, our study demonstrates that the m6A reader YTHDC2 promotes radioresistance of nasopharyngeal carcinoma via a translation-dependent pathway." (PMID 32850334, 2020). "The m6A reader YTHDC2 is up-regulated in radio-resistant nasopharyngeal carcinoma (NPC) cells." (PMID 40483535, 2025). "In nasopharyngeal carcinoma (NPC), YTHDC2 is highly expressed in radiation-resistant NPC cells." (PMID 35628460, 2022). "In nasopharyngeal carcinoma (NPC), an increased expression of m6A reader YTHDC2 was correlated with the activation of PI3K-Akt/S6 signaling conferring radioresistance to the cancer cells." (PMID 33814008, 2021). "Furthermore, YTHDC2 has been found to be highly expressed in radiation resistant nasopharyngeal carcinoma (NPC) cells, and YTHDC2 can bind to the mRNA of IGF1R and promote its expression." (PMID 38790013, 2024). "In nasopharyngeal carcinoma (NPC), YTHDC2 increased the translation efficiency and expression of IGF1R mRNA, thereby activating the downstream PI3K-AKT/S6 pathway, inhibiting tumor cell apoptosis, stimulating protein synthesis, and promoting radiotherapy resistance." (PMID 37264402, 2023).
colorectal cancer (7 papers, 2020 to 2025). A primary or metastatic malignant neoplasm that affects the colon or rectum. "Furthermore, downregulation of the RNA methylation regulator YTHDC2 has been associated with cuproptosis resistance in colorectal cancer, with YTHDC2 knockdown attenuating the anti-tumorigenic effects of elesclomol-Cu." (PMID 40406488, 2025). "The signature might provide five candidate targets (RBMX, FMR1, IGF2BP1, LRPPRC, YTHDC2) associated with specific clinical features, prognosis and improvement in immunotherapy for patients with colorectal cancer." (PMID 37194014, 2023). "To clarify the role of RBMX, FMR1, IGF2BP1, LRPPRC and YTHDC2, we analyzed the mRNA expression patterns in human colorectal cancer specimens." (PMID 37194014, 2023). "Interestingly, Wrn, Abcd4, Ythdc2, and Dync1h1 within this group are noted to have oncogenic function in colon, breast, gastric, and colorectal cancers, respectively." (PMID 36765634, 2023). "In addition, YTHDC2 exerts a promoting role in the colorectal cancer metastasis through the hypoxia/HIF-1α/Twist1 signaling pathway." (PMID 34497675, 2021). "In addition, here, we focused on the regulatory role of the m6A reader YTHDC2 in colorectal cancer." (PMID 35692505, 2022).
hepatocellular carcinoma (7 papers, 2020 to 2024). A malignant tumor that arises from hepatocytes. "Inducing ferroptosis, facilitated by m6A modification of ATG5 mRNA mediated by WTAP and YTHDC2, effectively suppresses hepatocellular carcinoma development, highlighting a promising therapeutic approach." (PMID 39315094, 2024). "In addition, the upregulation of YTHDC2 expression has been observed in hepatocellular carcinoma (HCC), glioblastoma, and prostate cancer." (PMID 36245989, 2022). "In hepatocellular carcinoma (HCC), elevated m6A modification of ATG5, driven by WTAP and recognized by YTHDC2, induces autophagy and promotes ferroptosis, thereby inhibiting HCC progression." (PMID 39695216, 2024). "Studies have shown that YTHDC2 and METTL3 can promote the development of hepatocellular carcinoma." (PMID 34055974, 2021).
Infertility (7 papers, 2017 to 2024). "Previous studies have shown that although YTHDC2 knockout mice have developed into adulthood, both male and female adult mice are infertile." (PMID 35359444, 2022). "After YTHDC2 knockout, both male and female mice exhibited infertility, implying that YTHDC2 is essential for fertility." (PMID 34568313, 2021). "Consequently, YTHDC2 gene knockout mice exhibited significantly smaller testes and ovaries, alongside infertility." (PMID 38790013, 2024). "YTHDC2 plays an important role in the meiotic process of male and female germ cells, and the deletion may lead to infertility or infertility." (PMID 35538402, 2022). "Knockout of YTHDC2 in mice leads to infertility and smaller testes and ovaries." (PMID 35359444, 2022). "Knockout of YTHDC2 will hinder the development of mouse germ cells and lead to infertility." (PMID 36429081, 2022). "Of note, YTHDC2 gene knockout mice exhibited defects in spermatogenesis and infertility, without significant developmental defects elsewhere." (PMID 38790013, 2024). "Adult females with YTHDC2cKO were also found to have thin uterine walls and small ovaries, without developed follicles in the ovaries, implying that YTHDC2 knockout in female mice leads to infertility." (PMID 34568313, 2021).
pancreatic cancer (7 papers, 2020 to 2022). "YTHDC2 has been identified as a frequently mutated gene in pancreatic cancer patients and plays a role in tumor metastasis by increasing the translational efficiency of HIF-1α." (PMID 32547941, 2020). "YTHDC2 is also considered to be a frequently mutated gene in patients with pancreatic cancer." (PMID 33692959, 2021). "We conclude that YTHDC2 may be associated with pancreatic cancer susceptibility." (PMID 33692959, 2021). "On the contrary, it has been reported that YTHDC2 can act as an oncogenic protein in pancreatic cancer." (PMID 34149792, 2021).
esophageal cancer (6 papers, 2021 to 2023). A primary or metastatic malignant neoplasm involving the esophagus. "SNP rs2416282 was obviously associated with the susceptibility of esophageal cancer by affecting YTHDC2 expression." (PMID 35220962, 2022). "Deletion of YTHDC2 promoted the proliferation of esophageal cancer cells through various cancer-related signaling pathways." (PMID 35220962, 2022). "From the TCGA database, we found that several m6A-associated genes, including YTHDF1, HNRNPC, ZC3H13, YTHDC2, and METTL14 were dysregulated in esophageal cancer compared to matched normal tissues." (PMID 34395102, 2021). "As a suppressor of esophageal cancer, YTHDC2 is lowly expressed in esophageal cancer." (PMID 33692959, 2021). "YTHDC2 was ascended in 9 cancers in lung squamous cell carcinoma (LUSC), esophageal carcinoma (ESCA), CHOL, LIHC and STAD." (PMID 37833468, 2023). "We found that HNRNPC, YTHDF, ZC3H13, YTHDC2, and METTL14 were dysregulated in esophageal cancer tissues." (PMID 34395102, 2021). "Based on TCGA pan-cancer correlation analysis, the results demonstrated that YTHDC2 significantly and positively correlated with ZNRD1-AS1 in all tumor types, with the exception of esophageal carcinoma (R > 0.3), including LUAD (R = 0.6139) and LUSC (R = 0.5741)." (PMID 36581942, 2022).